QSER1 (glutamine and serine rich 1)
Description:
Plays an essential role in the protection and maintenance of transcriptional and developmental programs. Protects many bivalent promoters and poised enhancers from hypermethylation, showing a marked preference for these regulatory elements over other types of promoters or enhancers. Mechanistically, cooperates with TET1 and binds to DNA in a common complex to inhibit the binding of DNMT3A/3B and therefore de novo methylation.
Synonyms: FLJ21924
Gene: Protein-coding gene on chromosome 11 (32,892,811 to 32,993,316, forward strand). Ensembl gene ENSG00000060749.
Subcellular location: Chromosome
Subcellular location (Human Protein Atlas): Nucleoplasm; Cytosol
Genetic constraint (gnomAD): Loss-of-function variants: 35 observed, 132.95 expected, observed/expected ratio (o/e) 0.26, 90% interval 0.2 to 0.35. The upper end of that interval is the gene's LOEUF score, 0.35, which puts it in group 1 of 6, group 1 being the genes least tolerant of losing a copy. Missense variants: 1,593 observed, 1,876.6 expected, observed/expected ratio (o/e) 0.85, 90% interval 0.81 to 0.88. Synonymous variants: 588 observed, 678.88 expected, observed/expected ratio (o/e) 0.87, 90% interval 0.81 to 0.93.
Homologues: Orthologues: macaque QSER1 (98% identical), chimpanzee QSER1 (92% identical), dog QSER1 (91% identical), pig QSER1 (91% identical), rabbit QSER1 (83% identical), guinea pig QSER1 (79% identical), mouse Qser1 (78% identical), rat Qser1 (77% identical), tropical clawed frog qser1 (59% identical), zebrafish qser1 (42% identical). Paralogues in human: PRR12 (30% identical).
Diseases named in the same sentence as QSER1 in open-access papers:
QSER1 is named in the same sentence as 7 diseases in open-access papers, as found by Europe PMC text mining. Sharing a sentence is not in itself a finding about the gene and the disease. The quoted sentences say what the papers report.
hyperopia (1 paper, 2008). A refractive error in which rays of light entering the eye parallel to the optic axis are brought to a focus behind the retina, as a result of the eyeball being too short from front to back. "Five of them were upregulated during induction of hyperopia with positive lenses (DCX, NLGN1, QSER1, TMTC3, and LOC41695) and one was downregulated (GRHL3)." (PMID 18769560, 2008).
Obesity (1 paper, 2018). Accumulation of substantial excess body fat. "Moreover, we observed candidate association of rs6271 in the DBH gene, rs62618693 in the QSER1 gene, and variants in PCDHA1, RAD51B, and PLEKHA5 with non-T2D-linked obesity." (PMID 30126146, 2018).
tumor (2 papers, 2013 to 2024). "A set of genes including PRPF38A, RIOK3, QSER1, PSMC3IP, ATAD3B, MGC12982, and C20ORF27 were significantly overexpressed in HCC-R tumor tissue with fold changes ≥4 (P = 0.001 to 0.0001)." (PMID 24377043, 2013).
adenocarcinoma (1 paper, 2018). A common cancer characterized by the presence of malignant glandular cells. "Next the LIMMA analysis of six Y73SV(+) and four Y73SV(−) adenocarcinoma specimens identified one up-regulated gene, MARCH3, and three down-regulated genes, NMNAT2, ANKRD29, and QSER1, in Y73SV(+) specimens." (PMID 30134863, 2018).
cancer (1 paper, 2023). A tumor composed of atypical neoplastic, often pleomorphic cells that invade other tissues.
QSER1 also shares sentences with these, for which no sentence is quoted: lung adenocarcinoma (1 paper); ovarian carcinoma (1).